ZNF24TR (ZNF24 transcription regulator)
Synonyms: ZNFTR; AC007998.3
Gene: Long non-coding RNA gene on chromosome 18 (35,437,887 to 35,467,090, reverse strand). Ensembl gene ENSG00000267583.
Diseases named in the same sentence as ZNF24TR in open-access papers:
ZNF24TR is named in the same sentence as 5 diseases in open-access papers, as found by Europe PMC text mining. Sharing a sentence is not in itself a finding about the gene and the disease.
ZNF24TR shares sentences with these, for which no sentence is quoted: pancreatic cancer (3 papers); breast carcinoma (1); cancer (1); gastric cancer (1); tumor (1).